MYCN (MYCN proto-oncogene, bHLH transcription factor)
Diseases named in the same sentence as MYCN in open-access papers (continued):
Sharing a sentence is not in itself a finding about the gene and the disease.
medulloblastoma (162 papers, 1989 to 2025). A malignant, invasive embryonal neoplasm arising from the cerebellum. "We also uncovered wider relevance in MYCN-amplified MBSHH suggesting a mechanistic convergence of MYC-dependent pathways across poor-risk medulloblastoma groups." (PMID 39377369, 2025). "MYC/MYCN are the most frequent oncogene amplifications in medulloblastoma (MB) and its primary biomarkers of high-risk (HR) disease." (PMID 39377358, 2025). "Overexpression of MYC is commonly associated with group 3 medulloblastoma, occurring in almost a fifth of these neoplasms with MYCN accounting for approximately 5% of this." (PMID 37509034, 2023). "A recently published cancer dependency map of pediatric tumors identified LRP8 as an essential gene in pediatric Ewing sarcoma and medulloblastoma, all entities associated with MYCN amplifications." (PMID 37435859, 2023). "MYC family amplifications are linked to group 3 medulloblastomas, and MycN overexpression in mice results in medulloblastomas that have a gene expression pattern similar to group 3 tumors." (PMID 37894287, 2023). "Amplification of MYC or MYCN has been shown to be associated with poor survival in pediatric medulloblastoma, but are rare in adults." (PMID 36249063, 2022). "Amplification of MYCN is observed in 5–10% of medulloblastomas and is associated with poor prognosis." (PMID 33628735, 2020). "Consistent with these associations, transcriptome analysis of human WTC10 MYCN tumors from NES cells aligned closest to SHH medulloblastoma." (PMID 31204176, 2019). "Medulloblastoma is a childhood cancer where approximately 10% of cases are linked to the MYCN oncogene." (PMID 28358317, 2017). "Both MYC and MYCN amplifications further associate with an aggressive LCA medulloblastoma pathology." (PMID 22348395, 2012). "In addition, MYC gene amplifications, such as in children with group 3 MYCC/MYCN-amplified medulloblastoma tumors, predispose patients to relapse and poor survival." (PMID 36540431, 2022). "Later, by using the RCAS-TVA system, we showed that specific Atoh1-negative/glial fibrillary acidic protein (GFAP)-positive brain stem cells could generate MYCN-driven medulloblastoma by using a mutationally stabilized MYCNT58A viral construct." (PMID 28333115, 2017). "Similarly, overexpression of mutationally stabilized MYCN in progenitor cells of the mouse cerebellum generates MYCN-driven medulloblastomas." (PMID 27769070, 2016). "These GTML mice are predisposed to SHH-independent, MYCN-amplified medulloblastoma." (PMID 26029667, 2015). "Interestingly, MYCN is often found amplified in SHH type of Medulloblastoma and its expression is linked to poor patient outcome." (PMID 25915540, 2015).
medulloblastoma (continued). "In vitro treatment of GTML/Trp53KI/KI medulloblastoma-derived neurospheres with the Aurora-A kinase inhibitor MLN8237 (Alisertib) destabilized MYCN via disruption of the Aurora-A/MYCN complex and caused growth inhibition comparable to doxycycline-mediated genetic suppression of MYCN expression." (PMID 25533335, 2015). "The meta-analysis data also show that prognostic factors like metastatic stage, histology, MYC and MYCN amplifications, 10q loss, 17p loss, and 17q gain, previously reported for medulloblastoma as a single disease, remain prognostic in these combined series of all patients." (PMID 22358457, 2012). "In these MYCN-amplified medulloblastomas, MYCN emerges as a pivotal oncogenic driver, orchestrating uncontrolled cell growth and resistance to conventional treatments." (PMID 39802403, 2025). "Our triplet links also include 60 genes known to be recurrently mutated or overexpressed in medulloblastoma, including OTX2, MYCN, the Fanconi anemia proteins FANCA and FANCI, and others." (PMID 41279093, 2025). "Studies are ongoing to investigate the therapeutic potential of MYCN inhibitors in various cancers, including medulloblastoma, rhabdomyosarcoma, and NEPC." (PMID 39802403, 2025). "Because a subset of Group 4 medulloblastomas shows high expression of PRDM6 in conjunction with amplification of the MYCN oncogene, we decided to investigate potential synergies between PRDM6 and MYCN expression on tumor development from NES cells." (PMID 38992221, 2024). "Forcing MYCN expression in the hindbrain by the Glt1-promoter induced the development of tumors, which resemble human medulloblastoma (MB) with the highest similarity to group 3 MB28." (PMID 38001143, 2023). "MycN drives aerobic glycolysis in CGNPs and Shh-driven medulloblastomas in Smo M2 mice by acting downstream of Shh." (PMID 37894287, 2023). "While glucose metabolism in group 3 medulloblastomas and MycN-driven medulloblastomas in mice have yet to be investigated, it is likely that MYC reconfigures the metabolism to favor glycolysis in these tumors, as it does in other malignancies." (PMID 37894287, 2023). "We detect similar mechanisms in shaping circRNA expression in the pediatric cancer medulloblastoma implying a general MYCN effect." (PMID 37402719, 2023). "This class of medulloblastoma portrays the worst prognosis which is thought to be related to the high incidence of MYCN amplification." (PMID 37509034, 2023). "One challenge will be to determine if this effect is recapitulated in other cancers with recurrent MYCN amplification such as medulloblastoma and neuroendocrine prostate cancer or in the numerous cancers in which MYC is altered." (PMID 37958555, 2023). "This research extends our knowledge about MYCN functionality and is likely to be applicable to other cancers with dysregulated MYCN, as exemplified for medulloblastoma." (PMID 37402719, 2023). "Both copy number gains and amplification are noted in rhabdomyosarcoma; whereas, MYCN amplification is seen in medulloblastomas." (PMID 37046804, 2023). "Group 3 medulloblastomas (Myc/MycN status known in 7/16 patients, 2/7 with Myc amplification) was associated with a median PFS1stRD of 4.9 months (CI: 3.2–6.0) and median OS1stRD of 9.8 months (CI: 8.2–11.3)." (PMID 35158738, 2022).
medulloblastoma (continued). "Adult SHH-medulloblastoma have frequent upstream pathway alterations (PTCH1 and SMO mutations), but infrequent downstream alterations (SUFU, MYCN amplifications)." (PMID 36249063, 2022). "Refined diagnoses were observed in two cases of medulloblastoma via the presence of a loss-of-function variant in SUFU (P2803) and an activating missense variant in MYCN (P2624)." (PMID 35449451, 2022). "Swartling and colleagues in their study performed on a medulloblastoma mouse model showed that MYCN contributes to tumor initiation and progression." (PMID 33430425, 2021). "The combination of low doses of MK-8776 plus olaparib efficiently inhibited also the growth of SHH-driven medulloblastoma in vitro and in vivo, confirming its efficacy in a different MYCN-driven tumor model." (PMID 34508175, 2021). "Alongside genetic abnormalities, dysregulated epigenetic modifiers are also frequently observed in more aggressive medulloblastoma tumours, including those harbouring MYCN/MYCN abnormalities." (PMID 34195095, 2021). "In our study, among the three types of tumors examined, the highest expression of MYCN was found in medulloblastomas, which confirms the observations made in the previous reports." (PMID 33430425, 2021). "This review will provide a comprehensive synopsis of the biological role of MYCN and its family components, their interaction with distinct signalling pathways, and the implications of this network in medulloblastoma development." (PMID 34195095, 2021). "In this review, we have highlighted the relationship between MYCN and the paediatric brain tumour medulloblastoma, with an emphasis on the emerging therapeutic avenues to target this." (PMID 34195095, 2021). "Oliver’s team in research performed on a mouse model of medulloblastoma showed that MYCN promotes cell cycle gene expression; increase of MYCN expression level was there reported with significantly increased levels of E2F1 (3.7-fold), and E2F2 (6.1-fold)." (PMID 33430425, 2021). "It is known that MYCN and let-7 play a critical role in medulloblastoma tumorigenesis and progression." (PMID 35008302, 2021). "The constitutive and dysregulated expression of the transcription factor MYCN has a central role in the pathogenesis of the paediatric brain tumour medulloblastoma, with an increased expression of this oncogene correlating with a worse prognosis." (PMID 34195095, 2021). "In this review, we will focus on the role of the MYC family proteins, specifically MYCN, in different subgroups of the childhood brain tumour medulloblastoma (MB)." (PMID 34195095, 2021). "Silencing of PRMT5 in MYCN‐overexpressing NB cells or MYC-driven medulloblastoma cells leads to a decrease in MYCN and MYC protein levels and cell growth inhibition." (PMID 33628735, 2020). "The transplantation of forbrain MYCN(T58A) NSCs gives rise to gliomas, while cerebellum and brain stem MYCN(T58A) NSCs transplants give rise to medulloblastoma and primitive neuroectodermal tumors." (PMID 33628735, 2020). "In this study, we report the clinical and mutational profiles of 99 adult medulloblastomas, investigated for molecular group, coding mutations, TERT promoter mutations, MYC and MYCN amplifications, and survival outcome." (PMID 33172502, 2020). "Previously, we generated a GEMM of medulloblastoma driven by misexpression of MYCN (referred as GTML)." (PMID 31204176, 2019).
medulloblastoma (continued). "Global transcriptome analysis also indicated that WTC10 MYCN tumors resembled medulloblastoma more closely than normal brain and other pediatric brain tumors (glioblastoma, pilocytic astrocytoma, and ependymoma)." (PMID 31204176, 2019). "WTC10 MYCN tumors showed similar focal changes in methylation in regions that overlapped 41% (27/66) of the DMRs found in medulloblastoma tumors from patients." (PMID 31204176, 2019). "Amplification of MYCN is normally found in SHH or group 4 medulloblastoma and rarely in group 3 tumors." (PMID 31204176, 2019). "Next, we compared molecular characteristics of tumors derived from MYCN NES cells (referred as WTC10 MYCN tumors) with human medulloblastoma patient tumors." (PMID 31204176, 2019). "Misexpression of MYCN in human NES cells transplanted orthotopically in mice generated medulloblastoma in vivo." (PMID 31204176, 2019). "Significantly, transcriptomes and patterns of DNA methylation from xenograft tumors were globally more representative of human medulloblastoma compared to a MYCN-driven genetically engineered mouse model." (PMID 31204176, 2019). "Literature review identifies the poor prognosis of MYCN-amplified medulloblastomas as well as extraneural metastases; we review the current limitations and future directions of medulloblastoma treatment options." (PMID 29343221, 2018). "Group 4 is the most prevalent group comprising 43% of all medulloblastomas and can be subdivided into three subgroups: Group 4α, characterized by MYCN amplification; Group 4β by CNCAIP duplication and Group 4γ by CDK6 amplification." (PMID 30279357, 2018). "In contrast, the weaker MycN/Miz-1 complex plays a role in SHH tumor development since inhibition of MycN/Miz1 binding blocked development of SHH medulloblastoma." (PMID 28333115, 2017). "Upregulation of MYCN has also been observed in proliferating neural precursor cells in medulloblastoma." (PMID 28358317, 2017). "High-level expression and amplification (~8%–9%) of MYCN occur in SHH medulloblastoma, with amplification being predictive of a worse prognosis." (PMID 28333115, 2017). "The GTML model gives rise to tumors that mostly (>80%) resemble Group 3 medulloblastoma but also smaller sets of WNT, SHH, and Group 4 tumors accentuating MYCN as a pleiotropic transcription factor in medulloblastoma tumorigenesis." (PMID 28333115, 2017). "Amplification and overexpression of the MYC oncogene family, especially c-MYC and/or MYCN, have been described in medulloblastoma." (PMID 28333115, 2017). "SHH has been related to both basal cell carcinoma and medulloblastoma which, in some forms, have amplification of the MYCN locus." (PMID 28358317, 2017). "Highlights of the available literature suggest that targeting Aurora kinase A is an effective way of disrupting MYC stability in c-MYC/MYCN-dependent malignancies including medulloblastoma." (PMID 28333115, 2017). "In this study, we used Mycn mutants designed to produce a stabilized protein to help mimic the MYCN amplification seen in some SHH subgroup medulloblastomas." (PMID 27310018, 2016). "iFISH analysis is considered the “gold-standard” for analysis of the MYC and MYCN copy number status in medulloblastomas in neuropathological practice." (PMID 27781424, 2016). "We next validated MYCC or MYCN amplification by FISH for selected medulloblastoma cell lines from metastatic medulloblastoma patients." (PMID 27255663, 2016). "MYCN amplification is known to be an important marker for poor prognosis in the SHH subgroup of human medulloblastomas, and the combination of Shh and Mycn have been shown to cause medulloblastomas in mice." (PMID 27310018, 2016). "Loss of the Ptch receptor in these mice leads to constitutive activation of the downstream smoothened transmembrane protein, resulting in medulloblastomas driven by MYCN and GLI." (PMID 26029667, 2015).
medulloblastoma (continued). "To study MYCN-driven medulloblastoma, we used a subcutaneous flank allograft model where SmoWT cells were injected in to the flank of athymic nude mice." (PMID 26029667, 2015). "Selection of this experimental system was of particular interest given that GTML is a native transgenic model of medulloblastoma driven by fully reversible expression of MYCN, allowing direct assessment of its role in spontaneous tumor development." (PMID 25533335, 2015). "MYCN is highly expressed in two of the medulloblastoma subgroups, the Sonic Hedgehog (SHH) group and the Group 4 tumors." (PMID 26029667, 2015). "Group 4 medulloblastomas are associated with CDK6 and MYCN amplification but minimal MYC over-expression." (PMID 25101241, 2014). "MYCN amplification and consequent overexpression has been also found in other cancers of neural origin, including glioblastoma, medulloblastoma, retinoblastoma, small cell lung carcinoma, peripheral neuroectodermal tumors." (PMID 24515800, 2014). "Currently, there is insufficient evidence, both for analytical and clinical performance of MYCN gene amplification status testing in medulloblastoma." (PMID 23618424, 2013). "Recent data suggest that MYCN amplified medulloblastomas comprise two different molecular subgroups with different clinical characteristics and prognosis." (PMID 23618424, 2013). "Recent data shows that even low-level copy number gain of MYCN can significantly influence patient outcome in medulloblastoma." (PMID 21533284, 2011). "MYCN can also be overexpressed in other tumours including medulloblastoma, retinoblastoma, small cell lung cancer, glioblastoma and other embryonal tumours suggesting the implication of MYCN dosage in cancer development and aggressive expressivity." (PMID 20017904, 2009). "To address the potential contribution of MYC or MYCN, we screened gene expression microarray data of 27 medulloblastoma specimens that were among 64 previously reported tumors." (PMID 16968546, 2006). "Despite these challenges, MYCN inhibitors hold promise as a crucial component in the evolving therapeutic landscape against MYCN-driven medulloblastomas, potentially ushering in a new era of more effective and less debilitating treatments for affected children." (PMID 39802403, 2025). "Amplification of the MYC transcription factor family member MYCN drives a range of solid tumours including medulloblastoma, rhabdomyosarcoma, osteosarcoma, Wilms tumour, small cell lung cancer and retinoblastoma, with MYCN overexpression associated with poorer prognoses." (PMID 38943005, 2024). "We detected several enhancer-hijacking events, an ecDNA containing the MYCN gene, and rare structural rearrangements, such a chromothripsis in a G4 medulloblastoma, chromoplexy involving 8 different chromosomes, a TERT gene rearrangement, and a PRDM6 duplication." (PMID 37576901, 2023). "Consequently, the genomic and functional alterations of MYCN represent a major therapeutic target to attenuate tumour growth in medulloblastoma." (PMID 34195095, 2021). "In addition, JQ1 has been shown to efficiently target MYC/MYCN transcription in pediatric NB and medulloblastoma." (PMID 34565342, 2021). "However, aberrations in RB1 and MYC/MYCN as well as leptomeningeal dissemination are characteristics of embryonal tumors as medulloblastomas or atypical teratoid rhabdoid tumors." (PMID 33876327, 2021).